ADORA2B (adenosine A2b receptor)
Diseases named in the same sentence as ADORA2B in open-access papers (continued):
Sharing a sentence is not in itself a finding about the gene and the disease.
heart disease (1 paper, 2023). "A study on heart disease showed that APIP was correlated with ADORA2B mRNA levels." (PMID 37938149, 2023).
metabolic disorders (1 paper, 2022). "Abraham and colleagues showed that air pollutants, including PM10 and NO2, could be associated with 27 DMRs, of which some are involved with genes that are implicated in pre-eclampsia, hypertensive and metabolic disorders, such as adenosine A2b receptor (ADORA2B)." (PMID 36429769, 2022).
psychiatric diseases (1 paper, 2022). "There is a growing amount of evidence that adenosine receptor genes such as ADORA1, ADORA2, ADORA2B, and ADORA3 have a neuroprotective role in various psychiatric diseases." (PMID 35599764, 2022).
ADORA2B also shares sentences with these, for which no sentence is quoted: lung carcinoma (3 papers); esophageal cancer (2); familial idiopathic pulmonary fibrosis (2); migraine (2); preeclampsia (2); bladder cancer (1); bladder urothelial carcinoma (1); brain ischemia (1); chronic obstructive pulmonary disease (1); depression (1); dyslipidemia (1); emphysema (1); epilepsy (1); erectile dysfunction (1); hearing loss (1); Hyperglycemia (1); Hypertension (1); influenza infection (1); invasive breast carcinoma (1); lung (1); mesothelioma (1); peritonitis (1); pneumococcal pneumonia (1); prostate carcinoma (1); Proteinuria (1); psoriasis (1); serous ovarian carcinoma (1); thyroid cancer (1); Tricuspid regurgitation (1); type 1 diabetes (1).
A further 1 disease shares a sentence with ADORA2B in 1 paper.